TRPV1 (transient receptor potential cation channel subfamily V member 1)
Diseases named in the same sentence as TRPV1 in open-access papers (continued):
Sharing a sentence is not in itself a finding about the gene and the disease.
cervical carcinoma (15 papers, 2012 to 2025). A carcinoma arising from either the exocervical squamous epithelium or the endocervical glandular epithelium. "In addition to this, the in vitro results of this study showed that overexpression of TRPV1 was associated with increased cell viability and colony formation, making it a potential candidate biomarker to predict the responses of cervical cancer cells to chemoradiation." (PMID 36230965, 2022). "In cervical cancer, TRPV1 promotes autophagy-mediated EGF secretion via Ca2+ influx, which induces the acquisition of cisplatin resistance." (PMID 39744692, 2025). "Over-expression of TRPV1 significantly increased the proliferation and clonogenic ability of cervical cancer cells." (PMID 40007993, 2025). "TRPV1 inhibition using a small-molecule agent AMG9810 can effectively overcome cisplatin resistance in cervical cancer cells." (PMID 39744692, 2025). "High expression of TRPV1 significantly enhances the proliferation and clonogenic ability of cervical cancer cells.TRPV1 in combination with PTEN is an effective prognostic marker for cervical cancer." (PMID 40007993, 2025). "TRPV1 expression in cervical cancer tissues was higher than that in precancerous epithelial tissues and normal epithelial tissues, and its up-regulated expression was significantly correlated with more advanced tumor stage and poorer tumor grading." (PMID 40007993, 2025). "Intrathecal resiniferatoxin, an ultrapotent capsaicin analog, ablates TRPV1-expressing nerve endings exposed to the cerebrospinal fluid, resulting in permanent analgesia in women with cervical cancer metastasis to the pelvic bone." (PMID 38339399, 2024). "For example, the TRPV1 antagonist capsazepine has shown some effectiveness in inhibiting the proliferation and invasion of cervical cancer cells." (PMID 38784033, 2024). "Some studies have found that the expression of TRPV1 in cervical cancer tissue is significantly higher than that in cervical intraepithelial neoplasia and normal epithelial tissue." (PMID 36230965, 2022). "This study found that the expression of TRPV1 in cervical cancer, especially in cervical squamous cell carcinoma, was significantly decreased." (PMID 36072430, 2022). "Contassot and coworkers reported a strong expression pattern of CB1 and CB2, as well as of TRPV1, in cervical carcinoma cell lines and biopsies." (PMID 33375539, 2020). "The findings regarding the pro-apoptotic action of AEA in endometrial cancer cell lines are in keeping with the observations by Contassot and colleagues, who described AEA-driven cervical cancer cell apoptosis via TRPV1 activation." (PMID 33375539, 2020). "Similar approaches can be applied to cervical cancer, where a transient receptor potential vanilloid 1 (TRPV1) inhibitor may enhance the efficacy of existing treatments and potentially overcome resistance to cisplatin therapy." (PMID 40361464, 2025). "One of the most well-studied TRP channels in cervical cancer is TRPV1." (PMID 38784033, 2024). "The expression of TRPV1 in human cervical cancer cell lines and tissues has been reported." (PMID 36072430, 2022). "However, the specific mechanism of TRPV1 down-regulation in the progression of cervical cancer and its impact on the prognosis of patients with cervical cancer need to be further explored." (PMID 36072430, 2022). "Furthermore, the majority of cervical cancer patients suffer from significant pain, and increased TRPV1 expression in cervical carcinoma is consistent with patient pain data." (PMID 35455973, 2022). "We speculated that low expressed TRPV1 promotes cervical cancer tumorigenesis through YTHDF1/2/3, HNRNPA2B1, YTHDC1/2, ZC3H13, and METTL14 modification." (PMID 36072430, 2022). "In addition, TRPV1 expression has been also reported in human cervical cancer cell lines and tissues, and the endocannabinoid anandamide (AEA) induced TRPV1-dependent tumor cell apoptosis." (PMID 22523714, 2012).
cervical carcinoma (continued). "Finally, TRPV1 stimulation completely reverted the cannabidiol- (CBD-) mediated inhibitory effect on human cervical cancer cell invasion by blocking CBD-induced increase of TIMP-1 MMP inhibitor." (PMID 22523714, 2012). "Furthermore, we analyzed the overall survival (OS) and disease specific survival (DSS) data of cervical cancer, and found that the overall survival prognosis of patients with low expression of TRPV1 showed worse prognosis, while patients with high expression of TRPM1 showed worse prognosis." (PMID 36072430, 2022). "Therefore, TRPV1 may be a potential marker of cervical cancer and a promising anti-cancer drug candidate." (PMID 36072430, 2022). "We had previously reported that CVB3 infections rely on the activation of transient receptor vanilloid potential 1 (TRPV1) and found that inhibiting TRPV1 activity with SB-366791 significantly limited CVB3 infection of HeLa cervical cancer cells." (PMID 37139492, 2023). "However, no relevant studies have confirmed whether the increased TRPV1 expression is associated with cervical cancer progression through pathways such as ATP release, P2Y2 activation, and EGFR transactivation." (PMID 36230965, 2022). "Contrary to this, TRPV1-selective antagonist capsazepine (CZ) protected cells against AEA, suggesting that TRPV1 is involved in the mechanism of AEA-induced apoptosis in cervical cancer cell lines." (PMID 33167409, 2020). "On the other hand, CBD’s effects in lung, colorectal, prostate, and cervical cancers are largely dependent on some combination of CB1, CB2, and TRPV1." (PMID 33143283, 2020). "However, it is not clear whether TRPV1 is involved in the progression of cervical cancer through immune inflammatory response." (PMID 36072430, 2022).
Headache (15 papers, 2012 to 2025). Cephalgia, or pain sensed in various parts of the head, not confined to the area of distribution of any nerve. "TRPV1‐mediated CGRP release may also be associated with migraine headaches." (PMID 38961264, 2024). "Numerous studies have used capsaicin and TRPV1 antagonists to investigate the meningeal afferent and vascular function and suggested a solid role for TRPV1 in headache mechanisms." (PMID 36986537, 2023). "There have been numerous studies using capsaicin and TRPV1 antagonists to probe meningeal afferent and vascular function and these studies suggest a role for the channel in headache mechanisms." (PMID 30970581, 2019). "TRPA1 receptors are highly co-expressed in TRPV1-expressing neurons and these receptors interact functionally, which suggests that these neurons and receptors are involved in headache induction." (PMID 25077949, 2014). "We found that repetitive stress and dural injection of PACAP38 induced headache behaviour through TNF-a and TRPV1 pathways." (PMID 38802819, 2024). "In the central nervous system, TRPV1 expression has been shown in the TNC and in numerous other areas, many of which are involved in the processing during headaches." (PMID 26109436, 2015). "Here, we have shown that PACAP38-MrgprB2 induces stress-induced headache via TNF-a and TRPV1." (PMID 38802819, 2024). "We note that we did not strive for a specific model such as migraine headache but a robust model of craniofacial pain including TRPV1 activation affecting the first trigeminal branch." (PMID 23574808, 2013). "We previously confirmed that in alcohol withdrawal-induced headache mast cell degranulation mediated by MrgprB2 could induce headache behaviour via tumour necrosis factor-α (TNF-α) receptor and transient receptor potential vanilloid 1 (TRPV1)." (PMID 38802819, 2024). "The reductions of MMA blood flow, TRPV1 and CGRP immunoreactivity, and TRPV1 and TRPA1 mRNA expression, are all consistent with the hypothesis that TRPA1 receptors, co-expressed with TRPV1, play a critical role in environmental irritant-induced headache." (PMID 25077949, 2014). "Taken together, our results suggest that TRPV1 and TRPA1 but not TRPM8 channels likely contribute to the excitation of dural afferent neurons and the subsequent activation of the headache circuit." (PMID 22971321, 2012). "For the first time, this study shows increased expression of CGRP and TRPV1 in a model of non-traumatic raised ICP, suggesting that these molecules may be involved in the headache related behavior observed in this model." (PMID 35650312, 2022).
overactive bladder (15 papers, 2007 to 2025). Symptom of overactive detrusor muscle of the urinary bladder that contracts with abnormally high frequency and urgency. "TRPV1 is a cation channel that can be activated by various stimuli and plays a critical role in the pathophysiology of overactive bladder." (PMID 39544909, 2024). "In a clinical study of the use of intravesical BoNT-A injection in patients with an overactive bladder, a significant reduction of TRPV1-positive nerves was detected in bladder biopsy specimens." (PMID 31689912, 2019). "Agonists of TRPV1, capsaicin and resiniferatoxin, have been used for therapeutic purposes of bladder overactivity and interstitial cystitis, but their efficacy is limited." (PMID 27713353, 2010). "Agonists of TRPV1, capsaicin and resiniferatoxin, have been used for therapeutic purposes of bladder overactivity and bladder pain syndrome, but their efficacy is limited." (PMID 27713353, 2010). "Although capsaicin and RTX are selective TRPV1 agonists, and both drugs increase urinary bladder capacity following intravesical instillation in patients with bladder overactivity, there are marked differences between these drugs." (PMID 21206614, 2010). "TRPA1 up-regulation and TRPV1/TRPV4 down-regulation may account for the MGO-induced bladder overactivity." (PMID 32317986, 2020). "This may suggest that the overexpression of EP4 in the rodent bladder mediates the action of PGE2 on TRPV1, which is expressed in C-afferent, to induce bladder overactivity." (PMID 31467580, 2019). "The finding that both sensory (TRPV1-positive) and cholinergic nerves are involved in urinary tract disorders such as overactive bladders raises the question of whether these two systems are anatomically distinct." (PMID 23249422, 2012). "TRPV1-expressing afferents also mediate a number of pathological phenomena in the LUT, including bladder pain and overactive bladder; recent findings suggest that these afferents also participate in pelvic organ cross-sensitization." (PMID 22934013, 2012). "Although it is unclear at the moment if TRPV1 excitation enhances NGF release from urothelium, this neurotrophin was shown to induce bladder overactivity in experimental animals and was found in high amounts in the urine of OAB patients." (PMID 17561998, 2007). "This sequence of events could potentially heighten TRPV1 sensitivity in the DRG, leading to increased excitability of the DRG and exacerbation of overactive bladder symptoms in patients with prostatitis." (PMID 39544909, 2024). "One study showed that TRPV1 expression was significantly higher in women with overactive bladder (OAB) than in women without OAB and that the increased expression was closely correlated to OAB occurrence." (PMID 36135835, 2022). "Interestingly, individuals suffering from overactive bladder were effectively treated with TRPV1 agonists, capsaicin or RTX, which might have the capacity to destroy TRPV1 expressing neurons." (PMID 24861977, 2014).
pancreatic cancer (15 papers, 2020 to 2025). "It was reported that the up-regulation of TRPV1 expression is highly associated with pancreatic cancer, mainly via affecting the biological activity of axonal growth in tumors." (PMID 37333498, 2023). "First, we prepared siRNAs targeting CB2 and TRPV1, transfected them into two pancreatic cancer cell lines, and confirmed knockdown via western blot analysis." (PMID 40790027, 2025). "Resiniferatoxin, a capsaicin analogue antagonizing TRPV1, can induce apoptosis and reduce pain in pancreatic cancer." (PMID 38541624, 2024). "A higher expression of TRPV1 was reported in human primary brain cancers, chronic pancreatitis and pancreatic cancer, and breast and thyroid cancers." (PMID 38612571, 2024). "Here, the authors block TRPV1 using photothermal nanoparticles encapsulating a TRPV1 antagonist in different cancer types, which can enhance thermo-immunotherapy in pancreatic cancer models." (PMID 37120615, 2023). "TRPV1 is involved in sensing cancer pain, and is a potential target for inhibiting of cancer pain in pancreatic cancer." (PMID 36741321, 2023). "Excessive transient receptor potential cation channel subfamily V member 1 (TRPV1) expression has been linked with the development of colon and pancreatic cancers." (PMID 36499622, 2022). "Resiniferatoxin (RTX), another potent TRPV1 agonist, induces apoptosis and decreases cancer cell growth in pancreatic cancer cells." (PMID 32604833, 2020). "Pancreatic cancer cells could activate the SHH signaling pathway which increased the expression of CGRP and TRPV1 in the dorsal root ganglion in a concentration- and time-dependent manner, resulting in the pain of pancreatic cancer." (PMID 35132349, 2022). "In 2006 studies connected the role of TRPV1 channels to pancreatic cancer." (PMID 33925979, 2021). "TRPV1 might be controlling Zeb1 in pancreatic cancer as it has been shown in hepatocellular carcinoma." (PMID 33925979, 2021). "If so, silencing TRPV1-expressing nerves using capsaicin may protect against pancreatic cancer." (PMID 37371563, 2023). "TRPV1 can downregulate EGFR levels by inducing EGFR ubiquitination and degradation, thereby inhibiting the EGFR/MAPK signaling in pancreatic cancer cells." (PMID 36304985, 2022).
pancreatitis (15 papers, 2008 to 2026). Inflammation of the pancreas. "Pain and inflammation associated with pancreatitis has been shown to require transient receptor potential (TRP) channel TRPV1." (PMID 34829924, 2021). "In pancreatitis, TRPV1 is activated in pancreatic sensory nerves and spinal cord neurons, thereby inducing the release SP and CGRP, causing pain and inflammation." (PMID 36045746, 2022). "Referred hyperalgesia associated with caerulein-induced pancreatitis in mice depends on both protease-activated receptor-2 (PAR-2) and TRPV1, TRPV1 being a downstream transducer of the pronociceptive action of PAR-2 stimulation." (PMID 21420431, 2011). "In a cerulein-induced pancreatitis model, activation of TRPV1 on sensory neurons promoted neurogenic pancreatic inflammation." (PMID 20034385, 2009). "Earlier studies that have implicated TRPV1 in the context of pancreatitis have shown that TRPV1 levels are elevated in non-infectious animal models of pancreatitis." (PMID 41596312, 2026). "Considering the importance of TRPV1 in the pathogenesis of neurogenic inflammation, these drugs may be also helpful in the neuromodulation and management of pain in pancreatitis." (PMID 38541624, 2024). "In addition, active excitation of the capsaicin receptor TRPV1 in inflammatory diseases such as pancreatitis, nephritis, and pneumonia has been shown to promote inflammation." (PMID 35911651, 2022). "A few studies suggest the transient receptor potential vanilloid receptor 1 (TRPV1) gene might be involved in pancreatitis." (PMID 20034385, 2009). "Selective TRPV1 and TRPA1 antagonists reduce pain and inflammation in murine models of pancreatitis." (PMID 32824721, 2020). "In CP, TRPV1 in intrapancreatic nerves can be activated by intrapancreatic neurotrophic factors, including NGF and artemin, which are overexpressed in pancreatitis, resulting in the release of SP and CGRP in the dorsal horn." (PMID 31496955, 2019). "Studies have shown that TRPV1 transcripts are elevated in experimental non-infection animal models of pancreatitis." (PMID 32231022, 2020).
Cerebral ischemia (14 papers, 2016 to 2024). Restriction of arterial blood supply to the brain associated with insufficient oxygenation to support the metabolic requirements of the tissue. "As concerns the TRPV1 gene, it has been shown that brain channels are activated by ischemic stroke, causing neurological and motor deficits as well as infarction after brain ischemia." (PMID 39035772, 2024). "TRPV1 antagonism can block this bradykinin-induced increase in BBB permeability after cerebral ischemia underlining multiple and possibly synergetic pathways." (PMID 33806707, 2021). "Accordingly, TRPV1 inhibition has been demonstrated to have a neuroprotective role during brain ischemia in mice, and its expression is enhanced post-stroke." (PMID 37020858, 2023). "Cao and coworkers found that TrpV1 activation leads to a decrease in the volume of affected brain tissue after the induction of cerebral ischemia." (PMID 30417826, 2018). "We demonstrate that TRPV1-mediated pharmacological hypothermia reduces both primary cortical infarct area and secondary thalamic injury area following cerebral ischemia/reperfusion." (PMID 29247238, 2017). "On this basis, DEX’s inhibition of the TRPM2 and TRPV1 currents contributes to the prevention or limitation of brain injuries during cerebral ischemia." (PMID 27872485, 2016). "Furthermore, DEX efficiently has been reported to reduce cumene hydroperoxide/ADP-ribose-triggered TRPM2 and TRPV1 densities in the neurons of mice with cerebral ischemia." (PMID 37269788, 2023). "However, there have been no reports on overload Ca2+ entry via activations of TRPM2 and TRPV1 in rats with cerebral ischemia." (PMID 27872485, 2016). "Dexmedetomidine (DEX) may act as an antioxidant through regulation of TRPM2 and TRPV1 channel activations in the neurons by reducing cerebral ischemia-induced oxidative stress and apoptosis." (PMID 27872485, 2016). "TRPV1 exhibits ubiquitous expression throughout the brain, encompassing key regions such as the hippocampus, cortex, cerebellum, olfactory bulb, mesencephalon, and hindbrain, with its activation exerting a discernible impact on the pathophysiological state of cerebral ischemia." (PMID 37718934, 2024). "Therefore, we suggest that DEX involved changes of Ca2+ entry through activations of TRPM2 and TRPV1 channels and the activations resulted in production of mitochondrial membrane depolarization-induced free oxygen radical in cerebral ischemia-induced brain HIPPO neuronal injury and pain induction." (PMID 27872485, 2016). "Therefore, we observed a TRPV1 activating role for cerebral ischemia induction in the neurons." (PMID 27872485, 2016). "Dexmedetomidine suppressed cerebral-ischemia-induced oxidative stress and apoptosis by inhibiting the activation of the TRPM2 and TRPV1 channels in neurons." (PMID 31682592, 2019). "The inhibitory effect of DEX in cerebral ischemia-induced TRPM2 and TRPV1 activation should be considered a potential pharmacological target for itching caused by cerebral ischemia-mediated activation of pain and brain injuries." (PMID 27872485, 2016). "In conclusion, results suggest that DEX treatment reduces cerebral ischemia-induced oxidative stress, cell death, and intracellular Ca2+ signaling through inhibition of TRPM2 and TRPV1 in the rat hippocampus and DRG." (PMID 27872485, 2016). "To address this interaction between DEX, TRPM2 and TRPV1, we investigated the protective actions of DEX treatment on apoptosis, oxidative stress levels, Ca2+ entry values as well as involvement of TRPM2 and TRPV1 activations on the values in the DRG and HIPPO neurons in rat with cerebral ischemia." (PMID 27872485, 2016). "The aim of the study was to evaluate whether DEX functionally interacts with TRPM2 and TRPV1 in the HIPPO and DRG neurons of rats with cerebral ischemia." (PMID 27872485, 2016).